NRP1 (neuropilin 1)
Diseases named in the same sentence as NRP1 in open-access papers (continued):
Sharing a sentence is not in itself a finding about the gene and the disease.
tumor (continued). "All genes were significantly down-regulated in 2D culture relative to the parental tumor, with the most differentially expressed markers including CD105, NRP1, FGFR3 and MMP2 (p < 0.005)." (PMID 26203665, 2015). "Similar to NRP1, NRP2 can bind to members of the VEGF family of growth factors, including VEGF-A, VEGF-C, and VEGF-D, which are overexpressed in tumor lymphatic vessels and play an important role in modulating lymphatic metastasis." (PMID 26398657, 2015). "In cancer patients, expression of NRP1, NRP2 or both NRPs is often upregulated and is correlated with tumor aggressiveness and advanced disease stage." (PMID 26030152, 2015). "It is suggested that the VEGF (VEGF165) can bind to NRP1 and then phosphorylate the VEGFR2 to trigger the NRP1/VEGFR2/PI3K/Akt signaling pathways for tumor angiogenesis and invasion." (PMID 26509169, 2015). "These compounds are cleaved on the membrane of tumor cells by a furin-like protease, which exposes a CendR motif (RGDK/R), allowing their interaction with NRP-1 and the internalization of the complex, along with a potential peptide-linked cargo." (PMID 26090340, 2015). "Neuropilin 1 (NRP1), a receptor of vascular endothelial growth factor (VEGF), promotes angiogenesis, tumor growth, tumor invasion and metastasis." (PMID 25954957, 2015). "NRP1 forms complexes with Flk-1/KDR (VEGFR2) to enhance the binding of VEGF165 to VEGFRs, and promotes VEGF165-mediated tumor angiogenesis, cell migration and tumorigenicity." (PMID 25954957, 2015). "Thus, it has been proposed that endothelial VEGFR2 may interact with tumor NRP1 in trans." (PMID 24521511, 2014). "The current study demonstrated that NRP-1 and VEGFR-2 were expressed in peritumoral liver tissue, mainly in the hepatocyte, at a markedly higher level than that in tumor tissue." (PMID 25333267, 2014). "Nrp1 expression on TIL corresponded with an antigen-experienced CD45RO+ phenotype, implying a possible connection with tumor/self-antigen reactive T cells." (PMID 25343644, 2014). "In contrast, Nrp1 was expressed on CD4+ and even more so on CD8+ TIL in a majority of patient tumor samples." (PMID 25343644, 2014). "Although NRP-1 and VEGFR-2 are expressed on endothelial cells and tumor cells, their expression in the corresponding peritumoral tissues has not been examined, especially in the peritumoral liver tissue of HCC patients." (PMID 25333267, 2014). "Previous studies have shown that NRP-1 acts as a co-receptor for VEGFR-2/VEGFA, and NRP-1 mediates a VEGFA/NRP-1/VEGFR-2 pathway, leading to tumor angiogenesis." (PMID 25333267, 2014). "Subsequent investigations identified NRP-1 as a receptor for the vascular endothelial growth factor (VEGF)-A isoform VEGF-165 in both endothelial cells and some tumor cells." (PMID 24736504, 2014). "Our mouse xenograft studies further showed that the expression of both NRP-1 and VEGFR-2 significantly declined as the tumor xenograft grew." (PMID 25333267, 2014). "Thus, a correlation between Nrp1 expression and tumor/self-reactive could be made." (PMID 25343644, 2014). "We further found that high peritumoral NRP-1 and VEGFR-2 expression also correlated with smaller primary tumor size and fewer satellite lesions." (PMID 25333267, 2014). "Moreover, the reduced tumor D-MVA could be restored in the tumors that overexpressed NRP1." (PMID 24736504, 2014). "Neuropilin-1 (NRP-1) is a novel receptor of vascular endothelial growth factor 165 that promotes angiogenesis, tumor growth, tumor invasion and metastasis." (PMID 23251257, 2013). "Recently, a tumor-penetrating peptide, iRGD (CRGDKGPDC), was identified and reported to increase vascular and tissue penetration in a tumor-specific and neuropilin-1-dependent manner, as compared to conventional RGD peptides." (PMID 23691500, 2013). "Neuropilin-1 (NRP-1) was found to be a receptor or co-receptor for the specific isoform VEGF165 and expressed on endothelial cells (ECs) and several types of tumor cells." (PMID 24385810, 2013).
tumor (continued). "Taken together, these studies allude to the possibility that Nrp-1 expression may be a good indicator for distinguishing between peripherally induced adaptive Treg cells and may be particularly suitable in deciphering the composition of tumor-infiltrating Foxp3+ Treg cells." (PMID 23874336, 2013). "Nonetheless, silencing of NRP-1 alone resulted in a complete abrogation of tumour formation by the HT1080 cells, indicating that NRP-1 plays a dominant role in angiogenesis and HT1080 tumour growth." (PMID 23185562, 2012). "An in vitro study using mouse embryonic mesenchymal stem cells has shown that tumor cell-derived PDGF-B plays an important role in the differentiation and recruitment of PCs through NRP1 signaling." (PMID 22007214, 2012). "NRP1 is a co-receptor for VEGF and is expressed on ECs, tumor cells and vascular smooth muscle cells." (PMID 22007214, 2012). "Immuno-histochemical (IHC) analyses of these sections revealed that the tumour cells themselves expressed various angiogenic markers like PECAM, VE-Cadherin, VEGF, VEGF165, NRP-1 and VEGFR-2 (FLK1/KDR) (Figure." (PMID 23185562, 2012). "NRP-1 and NRP-2 are expressed in several types of tumour cells; in many cancers the expression of one or both has been correlated with tumour progression and/or poor prognosis." (PMID 23185562, 2012). "The densities of VEGR1 and VEGFR2 were varied from 0 to 10,000 receptors/tumor cell, and the densities of NRP1 and NRP2 were varied from 0 to 100,000 receptors/tumor cell." (PMID 22104283, 2011). "In another study, Kigel and colleagues transfected breast cancer cells expressing NRP1 and-or NRP2 with each semaphorin to analyze their role in tumor progression in xenograft experiments." (PMID 24212788, 2011). "Later, anti-NRP1 monoclonal antibodies were shown to block VEGF-binding to NRP1 and to have an additive effect with anti-VEGF therapies to reduce tumor growth." (PMID 24212788, 2011). "When NRP1 co-receptors are present on myocytes in the normal compartment, a significant change in the concentration of free VEGF in the normal tissue and tumor is observed (case E compared to Baseline Model 2)." (PMID 22104283, 2011). "This is supported by observations that NRP1 and VEGF receptors are typically present in many types of parenchyma, e.g. hindbrain, astrocytes, tumor, and skeletal muscle." (PMID 21535871, 2011). "Several membrane PGs, including SDC-1, SDC-4, NRP-1, and CSPG4 can potentially present GAG chains on the surface of tumor cells." (PMID 21658254, 2011). "Receptors for VEGF (e.g., VEGFR1, VEGF2, Nrp1, Nrp2) are expressed on multiple cancer cell lines, and there is evidence that VEGF can function as a cell survival factor for tumor cells and vascular endothelial cells within the tumor." (PMID 20628530, 2010). "Cancer cells secrete VEGF-A as different isoforms that diffuse through the tumour microenvironment and bind to the specific transmembrane receptors VEGFR1, VEGFR-2 and neuropilin-1, mainly located on vascular endothelial cells (ECs)." (PMID 20334641, 2010). "Neuropilin-1 and NRP2 are present in various tumour types from patient specimens and overexpressed NRP1 or both NRPs correlate with tumour growth, disease progression, and patient prognosis." (PMID 20087344, 2010). "The model revealed that up to half of the VEGF distribution in the healthy tissue and the tumor with 100,000 NRP1 per endothelial cell, is in the form of a complex where VEGF165 is bound to VEGFR2 and NRP1 simultaneously." (PMID 18713470, 2008). "With these limitations, we observed that class-3 semaphorins (A–G) and their receptors NRP1/NRP2 as well as SEMA4D and VEGF expressions were heterogeneous between samples, which suggest a differential expression of these genes between tumours." (PMID 18781179, 2008).
tumor (continued). "Barr and co-workers showed that NRP-1 plays an essential role in autocrine antiapoptotic signaling by VPF/VEGF in tumor cells and that an NRP-1-blockade with an anti-NRP-1 peptide corresponding to exon 7 of VEGF165 induces tumor cell and EC apoptosis." (PMID 18000534, 2007). "For example, peptides containing the ‘CendR’ motif, such as tLyP-1 (CGNKRTR), bind to neuropilin-1 (NRP-1)—a receptor involved in tumor angiogenesis and metastasis—exhibiting tumor-specific tissue penetration and up to 4.8-fold increased tumor accumulation, as validated by SPECT/CT imaging." (PMID 41590805, 2026). "In the context of MB, this phenomenon may also reflect the complex immune–glia–tumor interactions within the TME, as another potential source of NRP1 influencing this vascular phenotype is TAMs, as suggested by the present study." (PMID 40805120, 2025). "Nrp-1 has been described as a marker for thymus-derived Treg cells, but is also known to play a role in the migration of Treg cells to VEGF-expressing tumors, and this results in increased tumor growth due to Treg cells suppressing anti-tumoral responses." (PMID 40977681, 2025). "NRP1 interacts with several key signaling pathways, including vascular endothelial growth factor (VEGF), semaphorins, and transforming growth factor-beta (TGF-β), modulating the tumor microenvironment and promoting angiogenesis." (PMID 40277760, 2025). "Regarding immune checkpoint genes, CD276 and NRP1 are positively correlated with the genes in our model, while TNFSF14 shows a negative correlation with these genes in the tumor immune microenvironment of high-risk patients." (PMID 40299539, 2025). "Neuropilin-1 (NRP1), a type I transmembrane glycoprotein, has emerged as a key player in tumor biology, with roles in angiogenesis and tumor progression through vascular endothelial growth factor (VEGF), transforming growth factor-beta (TGF-β), and placental growth factor (PlGF) signaling pathways." (PMID 40805120, 2025). "NRP1-mediated angiogenesis in ccRCC and NRP2-driven lymphangiogenesis and tumor invasion in SKCM demonstrate the complexity of TME dynamics, and their shared role in ECM remodelling and cancer immune evasion provides novel insights into effector mechanisms of M2-polarised macrophages in the TME." (PMID 40134439, 2025). "However, the shared structures and ligands (VEGFR1, NRP1, NRP2 and heparin) present opportunities to identify antibodies with dual-specificity to block both growth factors and thereby limit a mechanism of tumor resistance." (PMID 41306516, 2025). "Some NGR peptides possess a C-end Rule (CendR) motif, a C-terminal sequence motif that, when exposed, can mediate tissue penetration by binding to neuropilin-1, which, after initial binding and potential cleavage, can interact with neuropilin-1 (NRP-1) to enhance tumor penetration." (PMID 40564134, 2025). "As a result of the NRP-1 transport system playing a major role in the transport of these polyplexes, other HK peptides with a sequence of -KHHK- were tested for their ability to silence the tumor luciferase marker in vivo." (PMID 39683699, 2024). "Moreover, NRP1 is a co-receptor for vascular endothelial growth factor (VEGF), and blocking NRP1 can inhibit tumor growth by suppressing angiogenesis." (PMID 39679370, 2024). "Importantly, employing a Nrp-1 inhibitor alongside a 4-1BB agonist in humanized HCC models demonstrates favorable outcomes and safety, augmenting the anti-tumor effects of PD-1 blockade." (PMID 38571964, 2024). "Neuropilin-1 (NRP-1), a transmembrane glycoprotein, is overexpressed in GBM cells and serves as a co-receptor for semaphorin3A and vascular endothelial growth factor, contributing significantly to tumor angiogenesis, growth, and metastasis." (PMID 39409919, 2024).
tumor (continued). "Similar to iRGD-induced tumour import, the iRGD-induced elevation of the blood AFP concentration was blocked by a neutralizing anti-NRP-1 antibody and the timing of the two effects showed similar rapid onsets, indicating a close relationship between the two transport processes." (PMID 38889481, 2024). "Neuropilin-1 (NRP-1) and neuropilin-2 (NRP-2) function as co-receptors for members of the VEGF receptor family and are proven to be involved in vascular growth, in developmental angiogenesis, and tumor-driven angiogenesis." (PMID 39507419, 2024). "Thus, while NRP1 is dispensable for CD8+ T-cell priming and activation in flu-infected mice, the receptor plays an important role in anti-tumor responses." (PMID 38609390, 2024). "Similarly, neuropilin-1–/– Tregs produce IFN-γ, which drives the fragility of surrounding wild-type Tregs, boosts antitumor immunity, and facilitates tumor clearance." (PMID 38493212, 2024). "In addition, both NRP1 and YY1 are involved in the adaptation of tumor cells to hypoxia, a condition commonly observed in tumor microenvironment due to rapid consumption of oxygen for rapid proliferation and high metabolism." (PMID 38672608, 2024). "Although multiple enzymes within the tumor matrix can process HK peptides to bind to the NRP-1 receptor, the required processing of the peptides may decrease NRP-1-mediated uptake into the tumor." (PMID 39683699, 2024). "In the case of other RGD peptide types, they bind only to integrins and not to NRP-1 and are accumulated inside and/or around tumor vessels." (PMID 39594723, 2024). "In addition, cluster 25 relates to the regulation of VEGF-induced migration, including the expression of key VEGF-related genes (NRP1, NRP2, FLT1, KDR, PGF), which can promote tumour dissemination by supporting the invasion of malignant cells into the stroma." (PMID 38331751, 2024). "While tumor-penetrating C-end Rule (CendR) peptides hold promise for precision tumor delivery, C-terminally exposed CendR peptides can accumulate undesirably in non-malignant tissues expressing neuropilin-1 (NRP-1), such as the lungs." (PMID 39012578, 2024). "In our mouse model, NRP1 expression correlated with antigen exposure, and we therefore speculated that NRP1-positive CD8+ TILs might be tumor-specific." (PMID 38609390, 2024). "NRP-1 also acts as a co-receptor, enhancing the attachment of the vascular endothelial growth factor A (VEGF-A) to the VEGF receptor, a signaling pathway important in tumor angiogenesis." (PMID 39594723, 2024). "Consistent with previous reports on expression of Nrp1 in tumor and stromal cells in PDAC, Nrp1 immunoreactivity was found on tumor cells, parenchymal nerves and on vascular endothelial cells, but was only weakly present in epithelial cells of healthy pancreas." (PMID 38816706, 2024). "It implied that PEI-elastase broke the restrictions of receptor mediated endocytosis and achieved NRP1 negative tumor cell-killing ability." (PMID 39068444, 2024). "Gene expression of NRP1 is often but not always higher in tumor cells compared to corresponding non-tumoral tissue." (PMID 37894289, 2023). "In addition, we immunohistochemically validated the expression of NRP1, CXCR4, LGR6, CTLA4 and the key regulator of cuproptosis, ferredoxin 1 (FDX1), in nine paired tumor tissues and adjacent tissues." (PMID 37036489, 2023). "Furthermore, SEMA3B and its receptor, NRP-1, downregulate phosphatidylinositol-3-kinase (PI3K)/AKT signalling in breast cancer cells to restrict proliferation and inhibit tumour growth." (PMID 37685898, 2023). "First, we analyzed the differences in the expression of NRPs in PAAD tumor samples and normal pancreas samples, and the results showed that both, NRP1 and NRP2, were significantly more expressed in PAAD tumor samples (p < 0.001), and 17 other cancer types had similar results." (PMID 37190154, 2023).
tumor (continued). "Therefore, it can be inferred that PTX-SM-TAR has the targeting ability to NRP-1 and enter into cells through receptor-mediated endocytosis, which is helpful for PTX to target new blood vessels and tumor sites where NRP-1 is highly expressed." (PMID 36902076, 2023). "A7R peptide binds to both neuropilin-1 (NRP-1) and vascular endothelial growth factor receptor-2 (VEGFR2/KDR), disrupting their receptor/coreceptor interaction, and impacting, therefore, on angiogenesis and tumor growth." (PMID 37242749, 2023). "ACE2 and NRP1 play an important role in SARS-CoV-2 virus infection and tumor progression." (PMID 36875081, 2023). "In this report, we confirm that NRP1 is upregulated in transition to ADT, and further, our examination of human PCa datasets suggests that it may be present in 28% NEPC tumours." (PMID 36550208, 2023). "In both, the mouse tumor model and persistent gamma-herpes virus infection, the effect of Nrp-1 ablation was not analyzed in the early phase of disease, but approximately three weeks after inoculation or infection." (PMID 38019895, 2023). "Furthermore, expression of the co-receptor for VEGFR2, neuropilin-1 (NRP1), in tumor cells was considerably decreased in tumors after the bimodal therapy and chemotherapy alone." (PMID 38201461, 2023). "Together, our findings provide crucial insights into a novel NRP1/PKC axis to reveal promising new therapeutic targets in the treatment of PCa patients with NED and point to NRP1 as an early biomarker in tumour cell transition to the drug-resistant NE phenotype." (PMID 36550208, 2023). "Due to the important roles of VEGF-A165/NRP-1/VEGFR-2 in tumor angiogenesis, we propose that interrupting VEGF-A165 binding to VEGFR-2 or NRP-1 may be a practical method for anti-angiogenic therapy." (PMID 37240099, 2023). "We first analyzed NRP1 expression levels in human HCC samples from public databases, found significantly increased NRP1 expression in human HCC samples as well as its correlation with advanced tumor and metastasis stages." (PMID 36376373, 2023). "Moreover, NRP1 can activate EGFR phosphorylation, subsequently activating the downstream AKT-mTOR pathway, and ultimately contributing to tumor progression in PCa." (PMID 36841806, 2023). "This may suggest that Sema3A/NRP1/TGF-β axis-mediated signaling elicits protumorigenic effects by regulating tumor-autonomous proliferative pathways and the tumor microenvironment (TME)." (PMID 37788099, 2023). "Likewise, previous reports have described that NRP1 downregulation significantly reduced cell migration and cell proliferation in two in vitro models of HCC, as well as diminished tumor volume and vasculature in an HCC murine model." (PMID 36376373, 2023). "That investigation concluded that patients with higher levels of NRP1 in the peritumor tissue, but surprisingly not in the tumor, experienced longer OS and TTR." (PMID 35884516, 2022). "We performed Masson’s trichrome staining to observe tumor fibrosis and immunohistochemistry (IHC) staining to measure the expressions of PLGF, VEGFA, and their receptors (NRP1, VEGFR1, VEGFR2) using tissues derived from 10 PDAC patients with poor prognosis and 10 PDAC patients with good prognosis." (PMID 36272973, 2022). "In addition, Tr1 cells express Neuropilin-1 (Nrp-1), programmed cell death protein 1 (PD-1), and CD73, at an elevated level when they reside at the tumor site compared to tumor-draining lymph nodes (TdLNs)." (PMID 35860556, 2022). "NRP1/2-VEGFA was predicted to interact within M2 macrophages, which could potentially contribute to tumor angiogenesis." (PMID 35562760, 2022). "Regardless of tumor type, malignant cells overexpress NRP-1 and are thus more sensitive to the mitogenic effects of VEGF and other mediators." (PMID 36557705, 2022). "Therefore, NRP1 is essential for transmitting both VEGF and SEMA 3A signals to regulate tumor angiogenesis." (PMID 35600336, 2022).